IL18 (interleukin 18)
Diseases named in the same sentence as IL18 in open-access papers (continued):
Sharing a sentence is not in itself a finding about the gene and the disease.
metabolic syndrome (continued). "It has been proposed that the high circulating levels of IL‐18 in obese individuals is due to a compensatory production of IL‐18 in response to increased energy intake, which normally acts as a negative feedback signal to prevent metabolic syndrome." (PMID 38767114, 2024). "And it was also indicated that SUA might take part in stimulating the secretion of inflammatory markers such as C-reactive protein (CRP), interleukin (IL)-6, IL-18, and tumor necrosis factor (TNF)-alpha which are crucial to the development of metabolic syndrome." (PMID 35673358, 2022). "Notably, IL-1β, but not IL-18, participates in the development of metabolic syndromes by inhibiting adipocyte differentiation that is required for the maintenance of insulin sensitivity and inducing inflammation." (PMID 30717382, 2019). "Still, it remains to demonstrate whether muscle tissue could be a major source of circulating IL-18 in subjects with and without the metabolic syndrome." (PMID 20331890, 2010). "Also, in humans, elevated circulating levels of IL-18, a product of the activation of the nucleotide binding and oligomerization domain-like receptor family pyrin domain-containing 3 (NLRP3) inflammasome, have been identified in patients with metabolic syndrome." (PMID 36816031, 2023).
breast cancer (108 papers, 2011 to 2026). A primary or metastatic malignant neoplasm involving the breast. "In summary, high expression of IL-18 in breast cancer stromal area is associated with poor survival in breast cancer patients after surgery." (PMID 38031068, 2023). "Western blot analysis demonstrated that knockdown of ZNF‐148 increased the expression levels of pyroptosis‐associated biomarkers (NLRP3, ASC, IL‐1β, and IL‐18) in breast cancer cells, which was reversed by cotreating cells with NAC and ALA." (PMID 37909239, 2023). "But as far as we know, the higher serum IL‐18 level is associated with worse postoperative prognosis in patients with breast cancer." (PMID 38031068, 2023). "Both pyroptosis-related inflammasomes including NLRP1, NLRP3, NLRC4, AIM2, and the following inflammatory cytokines IL-1β and IL-18 are associated with the immune system in breast cancer." (PMID 36119049, 2022). "For example, Paclitaxel, Vinorelbine, Gemcitabine and Epirubicin are commonly used drugs to treat breast cancer, the expression levels of IL18 were negatively associated with tumor cell sensitivity to Paclitaxel, Vinorelbine and Epirubicin." (PMID 36138348, 2022). "Another study reported associations between two SNPs in the promoter of the IL-18 gene, c.-838C>A(rs1946518) and c.-368G>T (rs187238), and breast cancer risk." (PMID 30781715, 2019). "Increased levels of IL-18 have been detected in certain types of cancer, and elevated IL-18 expression has been associated with tumor growth and metastasis in breast cancer." (PMID 25780408, 2015). "Furthermore, there is evidence that IL-18 promotes breast cancer cell invasion and migration and is associated with the suppression of claudin-12 expression and activation of the p38–MAPK pathway." (PMID 36823153, 2023). "The IL18-607 and IL18-137 polymorphism contribute to increase the breast cancer risk." (PMID 36797662, 2023). "Additionally, leptin promotes the production of IL-18 and IL-8, which interfere with breast cancer cells and M2 tumor-associated macrophages, and thus stimulates tumor growth." (PMID 38202341, 2023). "To evaluate whether altered expression of the IL‐18 gene have an effect on YAP1, associated with breast cancer progression and metastasis, we studied the expression of IL‐18, IFNG and YAP1 genes." (PMID 34196131, 2022). "TNFα-238G>A polymorphism has been reported to alter the risk of several types of cancers, such as HCC, breast cancer, lung cancer, non-Hodgkin lymphomas, and prostate cancer.Interleukin-18 (IL-18) belongs to the IL-1 cytokine superfamily and it is a novel proinflammatory cytokine." (PMID 33773554, 2021). "In the context of the immune system and breast cancer, leptin is hypothesized to induce IL-18 expression both in TAMs (tumor-associated macrophages) and breast cancer cells." (PMID 34912237, 2021). "Altogether, our study highlights a new role for the inflammasome in promoting invasive breast cancer progression by facilitating tumor infiltration with neutrophils, while impeding the NK cell-associated anti-tumoral response independently of IL-1β and IL-18." (PMID 33042810, 2020). "Also, in Chinese Han women, a possible interaction between Interleukin-18-137G/C, −607G/T polymorphisms and BMI in breast cancer patients was identified." (PMID 32600328, 2020). "As expected, IL-18 was implicated in leptin-enhanced breast cancer cell invasion and migration." (PMID 31492049, 2019). "Recently, The IL-18 gene polymorphisms have been investigated in several cancers such as nasopharyngeal carcinoma, prostate cancer, colorectal cancer, esophageal carcinoma, cervical cancer, breast cancer and so on." (PMID 24066061, 2013). "Furthermore, reduced objective response rates following neoadjuvant treatment in individuals with metabolic syndrome-related breast cancer are linked to elevated serum levels of adipocytokines and IL-18bp (binding proteins to IL-18 and inhibiting its function)." (PMID 40584290, 2025).
breast cancer (continued). "Nevertheless, it is worth noting that the serum level of IL-18 declined in patients with thickened endometrium after tamoxifen therapy for breast cancer, which is a risk for the tumorigenesis of EC, indicating that IL-18 may be downregulated in tamoxifen-derived EC." (PMID 36531027, 2022). "The polymorphic genotypes of IL-18 promoter -607 and -137 were previously found to be associated with the risk of esophageal squamous cell carcinoma and prostate cancer in China, colorectal cancer in Greece, ovarian cancer in the USA (Hawaii), and breast cancer in Iran." (PMID 30925760, 2019). "Conversely, in malignancies such as renal cell carcinoma and breast cancer, IL-18 manifests prototypical antitumour characteristics, including enhanced immune surveillance and tumour cell apoptosis induction." (PMID 40738927, 2025). "Of the downregulated hub genes identified, IL18 was more highly expressed in all breast cancer subtypes relative to normal tissue, with the highest expression in the basal subtype." (PMID 41009689, 2025). "A recent paper found that in miR-200b-transfected breast cancer cells, the levels of IL-1β, IL-18, ASC, caspase 1, and NLRP3 were firstly increased by miR-200b, then enhanced by nobiletin." (PMID 39940319, 2025). "Gene expression analysis suggested the potential of NLRP3 inflammasome modulation to counterbalance breast cancer cells growth by activating the immunogenic cell death (pyroptosis) and inhibiting the activity of pro-inflammatory cytokines, IL-1β and IL-18." (PMID 39433537, 2024). "For example, leptin will not only promote TAMs through NF-κB/nuclear factor-κB1 (NF-κB1) but also the expression and secretion of interleukin-18 (IL-18) in breast cancer cells through the PI3K/AKT/ATF2 pathway." (PMID 38672455, 2024). "IL-18 also promotes the expression of transferrin, a positive regulator of cell growth and proliferation in breast cancer cells." (PMID 38732186, 2024). "Innate immune cytokines such as IL-1β and IL-18 have been shown to promote breast cancer progression in animal models." (PMID 39769450, 2024). "The activation of this complex determines caspase-1 maturation and activation of IL-1β and IL-18 which contribute to host-defense mechanism, inflammatory responses elaboration and breast cancer development." (PMID 39433537, 2024). "IL-18 plays an important role in inducing breast cancer cell migration by activating the p38 MAPK pathway and downregulating claudin-12." (PMID 38201482, 2023). "While one study recommended that high IL-18 gene expression detected in breast cancer tissues was a protective factor for breast cancer prognosis." (PMID 38031068, 2023). "The most frequently mentioned biomarkers for this cancer type came from the interleukin superfamily including IL-6, IL-8, IL-10, IL-2, IL-18, which is quite similar to what was found in breast cancer." (PMID 37181043, 2023). "And breast cancer cell-derived IL-18 also predicts a bad prognosis in patients with TNBC by increasing the immunosuppressive CD56dimCD16dim/- NK cell fraction and inducing PD-1 expression on NK cells." (PMID 38031068, 2023). "Caspase-1 in parenchymal cells of the tumor was negatively correlated with tumor progression, and upregulation of IL-18 in immune-stromal cells of breast cancer tissues is a potential immunotherapy target and a promising prognostic biomarker in this study." (PMID 38031068, 2023). "Caspase-1 in parenchymal cells of the tumor was negatively correlated with tumor progression, and upregulation of IL-18 in immune-stromal cells of breast cancer tissues is a promising prognostic biomarker and a potential immunotherapy target." (PMID 38031068, 2023). "The results showed that IL-18 in the immune-stromal cells and carcinoma cell embolus were the independent risk factors influencing the 5-year RFS of breast cancer patients." (PMID 38031068, 2023).
breast cancer (continued). "The proinflammatory cytokines serum amyloid A (SAA) and IL-18 are elevated in the serum of patients with recurrent breast cancer." (PMID 38169859, 2023). "Apart from breast cancer, it is proven that IL-18 participates in the pathogenesis and metastasis of gastric cancer and melanoma." (PMID 37686525, 2023). "In the parenchymal cells, ASC and IL-18 protein levels were significantly up-regulated in breast cancer tissues compared with adjacent normal tissues (P<0.05)." (PMID 38031068, 2023). "Studies have shown that breast cancer survivors with elevated IL-18 serum levels have shorter relapse-free survival durations than those with lower IL-18 levels." (PMID 36717689, 2023). "Different cellular sources and distribution often correlate with different functions, indicating the possibility of a more complex role for IL-18 in the tumorigenesis and development of breast cancer." (PMID 38031068, 2023). "IL-18 has shown antitumor activity in preclinical animal models such as lung cancer, breast cancer, sarcoma and melanoma." (PMID 37513021, 2023). "Three key inflammatory biomarkers associated with inflammation in breast cancer survivors are CRP, IL-6, and IL-18." (PMID 36717689, 2023). "Besides, the elevated protein level of IL-18 in the immune-stromal cells of cancer tissues, rather than tumor cells, was found closely associated with poor 5-year RFS, which indicates that IL-18 may be a key target for improving the long-term prognosis of breast cancer patients in the future." (PMID 38031068, 2023). "Even if the pro‐and anti‐tumorigenic mechanism of IL-18 coexist and is debated continuously, the tumor cell-derived and immune-stromal cell-derived IL-18 would predict a poor prognosis in breast cancer patients." (PMID 38031068, 2023). "Without distinguishing between fibroblasts and macrophages, we found that NLRP3, caspase-1, ASC, IL-1β, and IL-18 were all elevated in the breast cancer immune-stromal cells." (PMID 38031068, 2023). "IL-18 expression has been investigated as a possible prognostic indicator in breast cancer patients and augments the cytotoxicity of NK cells." (PMID 36901727, 2023). "Several cytokines like interferons (IFNs), IL-12, and IL18 inhibit breast cancer (BC) proliferation and invasion." (PMID 37675062, 2023). "Till now, much information has not been known about the role of YAP1 in tumor aggressiveness and immune evasion in breast cancer with respect to IL‐18." (PMID 34196131, 2022). "Patients having a higher expression of IL‐18 possess a better prognosis and higher YAP1 expression with lower IL18 drives to poor clinical results in breast cancer." (PMID 34196131, 2022). "In this work, we have shown that the level of IL-18 in saliva was equally increased in both fibroadenomas and breast cancer." (PMID 36286034, 2022). "Higher levels of IL1 β, IL1Ra, IL18, and IL1α in breast cancer tissues and significantly higher IL1 β levels in stage II, III or IV breast cancers were reported." (PMID 35686268, 2022). "It was shown that, compared with healthy controls, in the saliva of breast cancer patients, there is an increase in the content of both pro-inflammatory (IL-2, IL-6, and IL-18) and anti-inflammatory cytokines (IL-4 and IL-10)." (PMID 36286034, 2022). "IL-18 derived from breast cancer promoted PD-1 expression in NK cells and increased their immunosuppressive fraction, which is connected to bad outcomes in TNBC patients." (PMID 36119049, 2022). "It showed a low mRNA expression trend of GPX4, GSDMD and GSDMC in all three types of breast cancer cells, while the mRNA expression of IL18 varied." (PMID 36138348, 2022). "This can provide new approaches to better understand the relation between YAP1 and IL‐18 in breast cancer progression by performing in vitro and in vivo studies." (PMID 34196131, 2022).
breast cancer (continued). "For example, IL-1β promotes the proliferation, migration, angiogenesis, and release of HMGB1 in smooth muscle cells, while IL-18 promotes the migration of breast cancer cells by down-regulating claudin-12 and inducing the P38/MAPK pathway." (PMID 36233009, 2022). "In previous reports, ILs such as IL-18, IL-33, and IL-1α were found to have pro-tumorigenic effects in pancreatic cancer, breast cancer, and leukemia." (PMID 35954317, 2022). "It has been reported in a review that NLRP3, IL-1β, and IL-18 motivate the development of tumors in lung cancer, melanoma, and breast cancer." (PMID 36119049, 2022). "Our results suggest that a better prognosis in breast cancer is proportionate to higher expression of IL‐18." (PMID 34196131, 2022). "The results showed the expression and distribution of GPX4, GSDMD, GSDMC, IL18 in breast cancer and normal tissues." (PMID 36138348, 2022). "Our univariate cox regression analyses showed that IL-18 was a protective factor as well as GSDMC and TIRAP were risk factors for breast cancer prognoses." (PMID 34589498, 2021). "Activated pyroptosis induces the release of the inflammatory factors IL-1 and IL-18, thereby promoting breast cancer initiation." (PMID 34589498, 2021). "A three-gene regression model including IL18, GSDMC, and TIRAP was regarded as an independent risk factor of breast cancer prognoses." (PMID 34589498, 2021). "As shown in univariate cox regression analyses, IL-18, GSDMC, and TIRAP were significantly associated with survival outcomes of breast cancer." (PMID 34589498, 2021). "IL-18 was found to be increased in breast cancer patients compared to controls, and it is considered an important factor in inducing breast cancer cell migration." (PMID 32309219, 2020). "Anti-IL-18 antibodies have shown interesting results in multiple myeloma, while IL-18 delivery using oncolytic viruses or bacteria delay melanoma, colon or breast cancer growth." (PMID 33261061, 2020). "Some cytokines (IL-1, IL-6, IL-11) stimulate while others (IL-12, IL-18, IFNs) inhibit breast cancer proliferation and/or invasion." (PMID 32887217, 2020). "The results show that long-term exercise reduces IL-18 mRNA expression in breast cancer mice, and long-term running can inhibit IL-18 in the liver." (PMID 32309219, 2020). "High IL-18 levels were detected in patients with gastrointestinal disease, breast cancers, and in multiple myeloma; NLRC4 overexpression or high IL-18 levels contributed to a poor prognosis in gliomas and acute myeloid leukemia." (PMID 32983099, 2020). "In order to investigate how exercise in breast cancer affects inflammatory cytokines, IL-6, IL-18, TNF-α, and CRP mRNA expression levels were analyzed in the livers of the study mice." (PMID 32309219, 2020). "IL-18 levels were significantly increased in the breast cancer group (BC: 4.91 ± 0.36) compared to the control group (CTL: 1.00 ± 0.09, P < 0.001)." (PMID 32309219, 2020). "IL-18 is a pleiotropic cytokine that promotes antitumor pro-inflammatory responses and is highly expressed in breast cancer tumors in mice and in serum of breast cancer patients." (PMID 30781715, 2019). "A previous study showed that the IL-18BP-Fc therapy restrained the lung metastasis of breast cancer cells by blocking tumor-released IL-18." (PMID 31492049, 2019). "Conversely, others reported that NLRP3 inflammasome activation and the consequent release of IL-1β and IL-18 promoted tumor growth, proliferation, invasion, and metastasis in lung cancer, melanoma, breast cancer, and head and neck squamous cell carcinoma." (PMID 31200447, 2019). "Breast cancer-derived IL-18 triggered programmed cell death-1 (PD-1) expression on immunosuppressive NK cells and was associated with poor prognosis in patients with triple-negative breast cancer." (PMID 31492049, 2019).